AXL (AXL receptor tyrosine kinase)
Diseases named in the same sentence as AXL in open-access papers (continued):
Sharing a sentence is not in itself a finding about the gene and the disease.
melanoma (continued). "AXL, a tyrosine kinase receptor, is another potential target due to its notable elevated expression in many cancers, including melanoma." (PMID 38732242, 2024). "AXL enhances melanoma aggressiveness by activating the AKT (protein kinase B), p38 kinase, and MAPK signaling pathways." (PMID 39596009, 2024). "A significant increase in AXL expression was also detected in patients with progressive melanoma after targeted therapy." (PMID 37483492, 2023). "High expression of AXL in the majority of melanoma lymph node metastases limits treatment efficacy by promoting MM cell ability to a more aggressive mesenchymal phenotype switch from epithelial." (PMID 37795022, 2023). "The melanoma cell lines were classified as proliferative or invasive based upon their MITF/AXL expression activity." (PMID 36251678, 2023). "The reduction in melanoma invasion and migration following inhibition of AXL by its specific siRNAs or pharmacological inhibition confirms a significant role for AXL in the modulation of tumor progression and migration." (PMID 37370757, 2023). "ICA inhibited the expression of Axl receptor tyrosine kinase and immune checkpoint molecules in melanoma cells in vitro and improved the therapeutic response to cisplatin in mouse melanoma xenografts in vivo." (PMID 36978462, 2023). "In vitro studies have shown that AXL silencing via siRNA or pharmacological inhibition dramatically impedes the migration and invasion of melanoma cells." (PMID 37507910, 2023). "We also assessed how CDC20 knock-down would affect AXL expression in melanoma cell lines with relatively high levels of AXL (i.e. those classified as undifferentiated)." (PMID 38030698, 2023). "The study also revealed that HPF treatment downregulated melanoma progression markers, such as CD133, OCT-4, AXL, uPAR, and MMP-2, which are associated with tumor growth, metastasis, and EMT." (PMID 37507910, 2023). "AXL was prominently expressed in the sentinel lymph nodes of melanoma, suggesting a correlation with metastasis." (PMID 37147395, 2023). "The stratification of melanomas into distinct subsets by a gene-signature-dependent study revealed that AXL expression is correlated positively or negatively with identified gene signatures." (PMID 37370757, 2023). "This aggressive melanoma phenotype shows low MITF and high AXL expression, which causes early metastasis through pro-angiogenic factors such as VEGF and interleukin-8 (IL-8)." (PMID 36675114, 2023). "The elevated expression of AXL has been shown in many cancer types including melanoma, lung, breast, and pancreatic cancers." (PMID 37370757, 2023). "The set of genes that were positively associated with AXL expression were genes associated with extracellular matrix interactions and remodeling, indicating a possible role for AXL in melanoma invasion." (PMID 37370757, 2023). "MITF-low/AXL-high melanomas, characterized by low MITF expression and high AXL markers, are associated with intrinsic resistance to RAF/MEK inhibition therapy." (PMID 37239381, 2023). "It is thus tempting to propose that the actions of the GAS6/AXL signaling contribute to PCSK9-initiated immunosuppressive TME in melanoma." (PMID 36588164, 2023). "Accordingly, the most common marker of differentiated melanoma cells is the receptor tyrosine kinase (RTK) AXL." (PMID 37370757, 2023). "Both in our CDC20 promoter indel lines and in two other melanoma cell lines that are characterized by relatively high expression of AXL, we observed a significant reduction of AXL upon CDC20 knockdown by siRNA." (PMID 38030698, 2023). "High expression of AXL promotes the switch from an epithelial to a more aggressive mesenchymal phenotype in melanoma, limiting treatment efficacy." (PMID 37795022, 2023).
melanoma (continued). "Further in vitro and in vivo studies found that AR increased MITF protein degradation by modulating miRNA‐539‐3p/USP13 signalling, which resulted in increased melanoma cell invasion by increasing the expression of the receptor tyrosine kinase AXL." (PMID 35452181, 2022). "Here we employed pre-clinical melanoma models with high levels of AXL and investigated the anti-cancer effects and molecular mechanisms induced by the AXL inhibitor BGB324, when used alone and in combination with the BRAF inhibitor vemurafenib." (PMID 35332208, 2022). "In aggressive melanoma tumors, AXL and MITF levels inversely correlate, showing MITFlow/AXLhigh expression characterized by a slow proliferating state, invasion, and metastasis formation." (PMID 35956175, 2022). "In this melanoma cell line, celecoxib raised AXL expression in the last group as well compared to the control (Mean Diff." (PMID 35956175, 2022). "Altogether, these findings show that targeting AXL can be a central approach to suppress the invasive phenotype in melanoma." (PMID 35406721, 2022). "An additional example of success in combining CHK1 inhibitors with inhibitors of targets involved in the pro-survival pathway in melanoma was given by the observed synergistic effect in combining the AXL inhibitor BGB324 with the CHK1 inhibitor AZD-7762." (PMID 35563772, 2022). "A low MITF/AXL ratio predicts early resistance to multiple targeted drugs in melanoma, further linking dormancy mediating signals to melanoma plasticity." (PMID 35565234, 2022). "Of note, the expression of TYRO3, AXL, and MERTK, as well as their ligands, can be dramatically upregulated on immunosuppressive MDSCs in Braf-V600E/Pten deficient melanoma tumor-bearing C57BL/6 mice." (PMID 35572601, 2022). "This response corresponded with the largely variable MITF/AXL ratios from the cells, a well-known predictor of resistance in melanoma for which low ratios have been related with a multidrug-resistant phenotype." (PMID 36434616, 2022). "For instance, it was shown that miR-410-3p can upregulate AXL and drive a phenotypic switch towards an invasive phenotype in melanoma cells." (PMID 35406721, 2022). "Tirosh and colleagues found that cancer associated fibroblasts (CAFs) expressed high levels of AXL in melanoma tumours that also expressed high AXL but apparent low levels of MITF, both markers of therapeutic resistance." (PMID 35740696, 2022). "Accordingly, it was demonstrated that the combination of AXL-107-MMAE with MAPKi cooperate to inhibit melanoma growth in vitro and in vivo." (PMID 35406721, 2022). "Overall AXL expression is quite common among malignant melanomas and the possibility to potentiate targeted therapy by AXL inhibition is thus highly attractive." (PMID 35332208, 2022). "The receptor tyrosine kinase AXL has been found overexpressed in a wide range of cancers, including melanoma, and it was shown to mediate resistance to both target therapy (BRAF and MEK inhibitors) and immunotherapy." (PMID 35563772, 2022). "It is known that low-MITF/high-AXL expression signature is typical for invasive subpopulations of melanoma cells." (PMID 34063141, 2021). "Collectively, these data indicate that TNFα was a potent suppressor of the MITF transcription factor and the associated melanoma antigen Melan A, particularly in the transitory and melanocytic melanomas, whereas NGFR and AXL induction were variable." (PMID 34073253, 2021). "Slow-cycling melanoma cells with an invasive phenotype expressed high levels of the receptor tyrosine kinase AXL, which was one of the most strongly up-regulated genes in YFPlow/P3Flow compared with YFPhigh/P3Fhigh mouse RMS cells (logFC 2.6)." (PMID 34187933, 2021). "The expression of various receptor tyrosine kinases, including AXL, PDGFRB, and EGFR, in cutaneous melanoma occurs in MITFlow melanoma cells with a proinvasive potential and has been associated with BRAF/MEK inhibitor resistance." (PMID 33916908, 2021).
melanoma (continued). "The high ZEB1/TWIST1, low MITF, high AXL state promotes an invasive, dedifferentiated phenotype in melanoma while the high ZEB2/SLUG, high MITF, low AXL state promotes an anti-invasive, proliferative, differentiated phenotype." (PMID 35008286, 2021). "In melanoma, AXL inhibition, together with checkpoint kinase 1 and 2 (CHK1/CHK2) silencing, reduced the expression of DNA damage repair proteins and increased apoptosis." (PMID 33800547, 2021). "Nuclear AXL was detected in cultured non-small cell lung cancer cells, in schwannoma and melanoma samples by immunohistochemistry." (PMID 34638349, 2021). "The A375 cell line showed an upregulated AXL program in C2–C5, according to signatures taken from an earlier melanoma single-cell report and returned to baseline in C6 and C78." (PMID 34591417, 2021). "On average, MITF expression is reduced whereas the AXL expression level increased in the metastatic melanoma group, validating that MITFlow/AXLhigh melanoma cells represent metastatic melanoma more closely." (PMID 37849907, 2021). "In contrast, the upregulation of AXL by TNFα was variable and only observed in 6/40 melanoma cell lines tested." (PMID 34073253, 2021). "The western blot also elucidated that ST3GAL1, SOX2, GLI1, and AXL all have higher expression in metastatic melanomas as compared to primary melanomas." (PMID 35008286, 2021). "Another AP-1 family member, Fra1 (FOSL1), downregulates MITF through its transcriptional target, the chromatin modifier HMGA1, and induces the expression of AXL, driving melanoma cells to the MITFlow/AXLhigh state." (PMID 34604096, 2021). "We showed that the level of sAXL mirrors the levels of cellular AXL in melanoma cell lines and blood samples, and that treatment with the AXL inhibitor BGB324 or ERK/MAPK inhibitors reduced the levels of sAXL in cell media." (PMID 31917795, 2020). "It was shown that small subpopulations of AXL-positive cells are present in untreated melanoma samples, as well as patient-derived xenografts (PDXs), implying that they can be positively selected in the presence of BRAF/MEK inhibitors." (PMID 33291749, 2020). "In this study, we found that sAXL levels mirror the levels of cellular AXL in melanoma cell lines and patient samples." (PMID 31917795, 2020). "We then used several immune deconvolution tools to enumerate separate immune, stromal, and tumor cell populations, as well as melanoma-, AXL-, and MITF-related gene expression programs." (PMID 32296058, 2020). "The shRNA-mediated down regulation of CD133 or CD271 in melanoma cells revealed that both markers are inversely correlated, suggesting that CD133 suppresses genes associated with CD271, e.g., AXL and FOXD3 and vice versa." (PMID 32878000, 2020). "Overall, our data suggest that sialylated AXL is a major mediator of the pro-metastatic role played by ST3GAL1 in melanoma." (PMID 33203881, 2020). "Our work indicates that the receptor tyrosine kinase AXL is a major mediator of the pro-invasive effects of ST3GAL1 in melanoma." (PMID 33203881, 2020). "NME1LOW cells did not exhibit altered expression of mRNAs associated with differentiated melanocytes or transcripts encoding the putative melanoma virulence factors MITF, AXL, and JARID1b." (PMID 32029850, 2020). "Regarding protrusions, it has been recently shown that AXL invalidation enhances invadopodia formation in melanoma cells." (PMID 31963783, 2020). "Several clinical trials are currently underway in the U.S. to investigate AXL selective small molecule inhibitors such as BGB324/R428 in Melanoma (NCT02872259-Phase I & II) and TP-0903 in solid tumors (NCT03572634-Phase I & II)." (PMID 32922529, 2020). "In line with a previous publication in hepatocellular carcinoma, we observed a positive correlation between the expression of cellular AXL and the level of sAXL in media from melanoma cell lines." (PMID 31917795, 2020).
melanoma (continued). "This is consistent with earlier results demonstrating that melanoma cells expressed very little AXL and relied more on the MER and TYRO3 kinases." (PMID 32042425, 2020). "These discrepancies can be partially explained by high intratumour heterogeneity and coexistence of MITFhigh melanoma cells and MITFlow melanoma cells expressing the AXL kinase at a high level." (PMID 31354817, 2019). "At baseline, these three melanoma cell lines exhibited a low AXL/high MITF differentiated genetic signature." (PMID 30953519, 2019). "Expression of NFATc2, MITF, AXL, ZEB1, SNAI1 (encoding SNAIL), and CDH2 (N-Cadherin) was then evaluated at the mRNA level, by qPCR, in a larger panel of 30 melanoma cell lines." (PMID 30710146, 2019). "We selected these three melanoma cell lines to observe the parallel impact of TNFα and IFNγ on IL32 and the melanoma differentiation state because they exhibited a low AXL/high MITF differentiated genetic signature." (PMID 30953519, 2019). "The role of MITF in melanoma is controversial as low MITF/AXL ratio has been related to poor predictive response to targeted therapy in melanoma, while others have reported the involvement of MITF in unresponsiveness to MAPKi and melanoma progression." (PMID 29507054, 2018). "A bipolar expression characteristic for the three cell cultures was observed for AXL/MITF signature genes in agreement with recent melanoma single cell transcriptome analyses." (PMID 29614062, 2018). "While melanoma cells of the proliferative phenotype display a broad treatment sensitivity profile, it is the AXL‐high, invasive, and metastatic cells that are intrinsically difficult to target." (PMID 28694322, 2017). "These melanomas are characterized by gene signatures, which correlate with enhanced expression of the receptor tyrosine kinase AXL." (PMID 28606996, 2017). "The receptor tyrosine kinase AXL is expressed in cutaneous and uveal primary melanomas and cell lines and regulates cell growth, survival, and migration." (PMID 28103611, 2017). "At bulk‐tumour level, melanomas can be classified as either MITF‐high or AXL‐high, but single‐cell sequencing has revealed intra‐tumour heterogeneity, whereby MITF‐high melanomas also contain cells with elevated AXL expression." (PMID 28606996, 2017). "We also do not find a significant overlap between our core set of 95 genes DE in at least 3 of the 4 clutches and the gene signatures of either MITF high expressing or AXL high expressing human melanoma cells determined by single cell RNA-seq." (PMID 28806732, 2017). "TYRO3 induces MITF-M expression in a SOX10-dependent manner in melanoma cells, while other studies showed the anti-correlation between MITF and AXL in melanoma cells." (PMID 27102439, 2016). "AXL is also an important factor driving resistance to MAPK inhibitors in BRAF (V600) mutant melanoma." (PMID 27834845, 2016). "AXL is expressed in 6 out of the 9 melanoma cell lines tested, and PDGFRβ is expressed at high levels in three cell lines and at lower levels or undetectable in the others." (PMID 27102439, 2016). "AXL is activated in melanomas and engaged in an autocrine loop due to endogenous production of its ligand Gas6." (PMID 27102439, 2016). "We demonstrated the co-expression of RUNX2 with IGF-1R, EGF-R, PDGFRβ and AXL using ShRNA RUNX2-expressing melanoma cells and showed co-expression of RUNX2 with AXL in human melanoma samples." (PMID 27102439, 2016). "Another study analyzed active RTKs in melanoma cell lines through measurement of their level of tyrosine phosphorylation and found that AXL, TYRO3 and MER were among the RTKs with the highest overall activation level." (PMID 27102439, 2016). "To confirm the mRNA expression results, we performed an immunohistochemical analysis of RUNX2 and AXL in the same melanoma tissue microarray (TMA)." (PMID 27102439, 2016).
melanoma (continued). "Applying this model to the MITF‐positive and MITF‐negative populations would predict that melanoma cells reversibly switch between AXL‐/WNT5A‐ and AXL+/WNT5A+ cell populations." (PMID 25818589, 2015). "Melanomas with low levels of MITF are resistant to MAPK inhibitors and tend to exhibit high levels of NF-κB and AXL, while melanoma with high MITF levels exhibit low NF-κB activity and are more sensitive to MAPK inhibition." (PMID 26426052, 2015). "Nevertheless, this indicates that a third ‘class’ of melanoma cells exists where a particular intracellular signalling permits the co‐existence of MITF with AXL and WNT5A, which otherwise is mutual exclusive." (PMID 25818589, 2015). "Subtype-specific expression of key signaling proteins like AXL and other RTKs is also central to the signaling pathways inherently available to a given melanoma cell-type." (PMID 25742786, 2015). "MERTK-expressing melanoma cells are more proliferative than AXL-expressing cells, though the latter are more invasive." (PMID 24743024, 2014). "AXL expression is also elevated in leukemia, melanoma, prostate, colon, endometrial, and thyroid cancers." (PMID 17389914, 2007). "Although the critical roles of MITF and AXL in melanoma invasion and metastasis have been established, whether they exhibit distinct roles in brain metastasis remains unclear." (PMID 41284647, 2025). "AR also increased melanoma invasion through regulating the miRNA-539-3p/USP13/MITF/AXL signals." (PMID 41228208, 2025). "We next examined whether FRA1 promotes melanoma metastasis via transcriptionally activating AXL, CDK6, and Fascin expression." (PMID 41286309, 2025). "FRA1, like AXL, has been found to be an overexpressed gene in melanoma." (PMID 40869968, 2025). "AXL functions as an upstream regulator of AKT-mediated resistance to BRAF inhibitors in melanoma with wildtype PTEN, while AKT and Fascin regulate each other, creating potential feedback mechanisms that may stabilize the pro-metastatic state." (PMID 41286309, 2025). "An increase in AXL expression has been observed in melanoma after pharmacological therapy." (PMID 41013839, 2025). "Furthermore, pharmacological inhibition of CDK6 and FSCN1, and to a lesser extent AXL, suppressed melanoma metastasis and prolonged overall survival." (PMID 41286309, 2025). "Interestingly, AXL and Fascin have been implicated in reciprocal regulation with AKT, indicating complex regulatory networks controlling melanoma progression." (PMID 41286309, 2025). "In melanoma, high expression of AXL contributes to resistance against MAPK pathway inhibitors." (PMID 40739577, 2025). "In addition, an AXL+ CD45− CD8− melanoma lineage+ subpopulation of putative dedifferentiated melanoma cells was also detectable." (PMID 39697983, 2024). "which mentioned that the AXL program is expressed both in melanoma cells and CAFs." (PMID 39697983, 2024). "Besides p300, in melanoma, SOX2 forms a complex with GLI1 and cooperatively transactivates ST3GAL1, which promotes melanoma metastasis via upregulating AXL." (PMID 38331879, 2024). "Another group of genes and gene sets (e.g., AXL, HM angiogenesis, and HM inflammatory response) refers to the ST pattern associating with modules G and F. The gene S100A8 is reported to act as an early marker of melanoma development." (PMID 38785552, 2024). "Thus, HIF-1α can indirectly, via EMT induction, or directly via MITF/AXL expression, shift melanoma phenotypes towards immunosuppressive and metastatically-inclined states." (PMID 38426087, 2024). "Our results suggest that MITF+ melanoma cells are efficiently targeted by immunotherapy, while AXL+ melanoma cells may be more resistant." (PMID 39697983, 2024). "Apart from the significance of the MITF/AXL ratio in the development of resistance to BRAFi, MITFlow/JARID1Bhigh and MITFhigh/PGC1αhigh (PPARG coactivator 1 alpha) ratios also have been linked to drug resistance in melanoma." (PMID 38672652, 2024).